OTOL1 (otolin 1)
Description:
Collagen-like protein specifically expressed in the inner ear, which provides an organic scaffold for otoconia, a calcium carbonate structure in the saccule and utricle of the ear. Acts as a scaffold for biomineralization: sequesters calcium and forms interconnecting fibrils between otoconia that are incorporated into the calcium crystal structure. Together with OC90, modulates calcite crystal morphology and growth kinetics.
Synonyms: C1QTNF15; C1QTNF16
Tractability: Antibody: UniProt places it where antibodies can reach, with medium confidence; UniProt predicts a signal peptide or a membrane-spanning region; its Gene Ontology location is reachable by antibodies, with medium confidence.
Gene: Protein-coding gene on chromosome 3 (161,496,808 to 161,503,942, forward strand). Ensembl gene ENSG00000182447.
Subcellular location: Secreted, extracellular space, extracellular matrix
Gene Ontology:
Molecular function: calcium ion binding
Biological process: extracellular matrix organization; otolith mineralization; protein homooligomerization
Cellular component: extracellular region; non-collagenous component of interstitial matrix
Genetic constraint (gnomAD): Loss-of-function variants: 28 observed, 25.16 expected, observed/expected ratio (o/e) 1.11, 90% interval 0.82 to 1.52. The upper end of that interval is the gene's LOEUF score, 1.52, which puts it in group 6 of 6, group 1 being the genes least tolerant of losing a copy. Missense variants: 654 observed, 559.69 expected, observed/expected ratio (o/e) 1.17, 90% interval 1.1 to 1.25. Synonymous variants: 225 observed, 201.78 expected, observed/expected ratio (o/e) 1.12, 90% interval 1 to 1.25.
Homologues: Orthologues: chimpanzee OTOL1 (99% identical), macaque OTOL1 (93% identical), pig OTOL1 (81% identical), rabbit OTOL1 (77% identical), rat Otol1 (73% identical), guinea pig OTOL1 (72% identical), mouse Otol1 (72% identical), tropical clawed frog otol1 (58% identical), zebrafish otol1a (44% identical), zebrafish otol1b (43% identical). Paralogues in human: COL8A2 (34% identical), COL8A1 (34% identical), COL10A1 (33% identical), C1QTNF9 (25% identical), C1QTNF9B (25% identical), COL19A1 (24% identical), C1QTNF7 (21% identical), C1QTNF2 (21% identical), ADIPOQ (20% identical), C1QTNF5 (17% identical), C1QC (17% identical), C1QTNF3 (17% identical), and 11 more.
Diseases named in the same sentence as OTOL1 in open-access papers:
OTOL1 is named in the same sentence as 10 diseases in open-access papers, as found by Europe PMC text mining. Sharing a sentence is not in itself a finding about the gene and the disease. The quoted sentences say what the papers report.
inner ear disorder (3 papers, 2020 to 2024). A non-neoplastic or neoplastic disorder affecting the inner ear. "Serum concentrations of otolin-1 can potentially be used as a biomarker for the acute onset of inner ear disorders due to the significant increase in patients with BPPV." (PMID 39456211, 2024). "Serum concentrations of otolin-1 can potentially be used as a biomarker for the acute onset of inner ear disorders due to its significant increase in patients with BPPV." (PMID 39456211, 2024). "Both parathyroid hormone (PTH) and total calcium concentrations affect otolin-1 concentrations, implying that the calcium dysregulation caused by primary hyperparathyroidism may contribute to the otoconia breakdown and may be associated with inner ear disorders such as BPPV." (PMID 39456211, 2024).
Vertigo (3 papers, 2020 to 2026). An abnormal sensation of spinning while the body is actually stationary. "Higher PSQI scores were also associated with increased levels of Otolin-1 and otoconin-90, both of which were independently related to vertigo severity." (PMID 41836934, 2026). "The aim of this study was to determine whether otolin-1 levels change during vertigo episodes in patients with BPPV and whether any change is specific and sensitive enough for BPPV episodes." (PMID 32477244, 2020). "The aim of this study was, therefore, to explore whether serum levels of otolin-1 can serve as a biomarker for distinguishing between acute episodes of BPPV and matched healthy controls without vertigo symptoms." (PMID 32477244, 2020).
bipolar disorder (1 paper, 2015). A disorder of the brain that causes unusual shifts in mood, energy, activity levels and the ability to carry out day-to-day tasks. "We identified three rare deletions in KCNJ6, UNC13C, OTOL1 and 7 rare duplications in CNTNAP2/MIR548F3, CORO7/VASN, DTNB, EMID2, KCNF1, PDPR and SGTA/THOP1 that are present in children with bipolar disorder (and their parents)." (PMID 25887117, 2015).
chronic otitis media (1 paper, 2020). Chronic form of otitis media (disease). "Recently, another clinical study reported that serum otolin-1 levels significantly increased in patients who underwent mastoidectomy due to chronic otitis media and were independently associated with the duration of drilling." (PMID 32477244, 2020).
osteoporosis (1 paper, 2020). A condition of reduced bone mass, with decreased cortical thickness and a decrease in the number and size of the trabeculae of cancellous bone (but normal chemical composition), resulting in increased fracture incidence. "Additionally, Sacks and Parham found a strong correlation between otolin-1 levels, benign paroxysmal positional vertigo (BPPV), and osteoporosis." (PMID 33383894, 2020).
vestibular disorder (1 paper, 2022). Pathological processes of the vestibular labyrinth which contains part of the balancing apparatus. "The most upregulated gene in the OC/SGN is Otol1, which encodes OTOL1, a protein important for biomineralization and associated with vestibular disorders." (PMID 35454087, 2022).
OTOL1 also shares sentences with these, for which no sentence is quoted: Meniere disease (2 papers); primary hyperparathyroidism (2); hearing loss (1); noise induced hearing loss (1).